TIPRL (TOR signaling pathway regulator)
Description:
May be a allosteric regulator of serine/threonine-protein phosphatase 2A (PP2A). Isoform 1 inhibits catalytic activity of the PP2A(D) core complex in vitro. The PP2A(C):TIPRL complex does not show phosphatase activity. Acts as a negative regulator of serine/threonine-protein phosphatase 4 probably by inhibiting the formation of the active PPP4C:PPP4R2 complex; the function is proposed to implicate it in DNA damage response by promoting H2AX phosphorylated on Ser-140 (gamma-H2AX). May play a role in the regulation of ATM/ATR signaling pathway controlling DNA replication and repair.
Synonyms: TIP; MGC3794; dJ69E11.3; TIP41; TIPRL1
Tractability: PROTAC: ubiquitination databases record sites on it; its protein half-life has been measured.
Gene: Protein-coding gene on chromosome 1 (168,178,918 to 168,202,114, forward strand). Ensembl gene ENSG00000143155.
Subcellular location: Cytoplasm
Subcellular location (Human Protein Atlas): Vesicles
Gene Ontology:
Molecular function: protein binding; protein phosphatase inhibitor activity; protein phosphatase activator activity
Biological process: DNA damage checkpoint signaling
Cellular component: cytosol; cytoplasm
Genetic constraint (gnomAD): Loss-of-function variants: 5 observed, 17.05 expected, observed/expected ratio (o/e) 0.29, 90% interval 0.15 to 0.62. The upper end of that interval is the gene's LOEUF score, 0.62, which puts it in group 2 of 6, group 1 being the genes least tolerant of losing a copy. Missense variants: 192 observed, 251.26 expected, observed/expected ratio (o/e) 0.76, 90% interval 0.68 to 0.86. Synonymous variants: 83 observed, 89.42 expected, observed/expected ratio (o/e) 0.93, 90% interval 0.78 to 1.11.
Homologues: Orthologues: chimpanzee TIPRL (100% identical), macaque TIPRL (99% identical), rabbit TIPRL (97% identical), mouse Tiprl (97% identical), pig TIPRL (96% identical), guinea pig TIPRL (94% identical), rat Tiprl (83% identical), tropical clawed frog tiprl (76% identical), zebrafish tiprl (65% identical), Drosophila melanogaster CG9578 (38% identical), Caenorhabditis elegans ZK688.9 (37% identical).
Diseases named in the same sentence as TIPRL in open-access papers:
TIPRL is named in the same sentence as 29 diseases in open-access papers, as found by Europe PMC text mining. Sharing a sentence is not in itself a finding about the gene and the disease. The quoted sentences say what the papers report.
hepatocellular carcinoma (11 papers, 2017 to 2024). A malignant tumor that arises from hepatocytes. "Recently, it has been reported that TIPRL is overexpressed in hepatocellular carcinoma, and that knockdown of TIPRL by small interfering RNA causes sustained activation of MKK7 (mitogen-activated protein kinase kinase 7) and JNK (c-Jun N-terminal kinase) by increasing MKK7 phosphorylation." (PMID 32719745, 2020). "We recently reported that the human TOR signaling regulator (hereafter TIPRL) contributes to the drug-resistance of hepatocellular carcinomas (HCCs) and the involvement of TIPRL/LC3/CD133 in liver cancer aggressiveness." (PMID 34208132, 2021). "In hepatocellular carcinoma samples and cell lines, TIPRL is overexpressed and prevents TRAIL-induced apoptosis through inactivation of MKK7-JNK signaling, thereby representing a potential biomarker for early liver cancer." (PMID 32719745, 2020). "TIPRL is highly upregulated in hepatocellular carcinomas (HCCs) compared with the adjacent liver tissues, and negatively regulates the MKK7/JNK axis, thereby preventing prolonged activation of MKK7 and JNK and, as a consequence, TRAIL-induced apoptosis." (PMID 31727942, 2019). "The TOR signaling pathway regulator-like protein (TIPRL), upregulated in hepatocellular carcinoma cells, inhibits MAP2K7-JNK activation through binding of TIPRL to MAP2K7 and protein phosphatase type 2A (PP2Ac), causing dephosphorylation of MAP2K7 and preventing TRAIL-induced apoptosis." (PMID 39717752, 2024). "Previous studies have shown that TIPRL is highly expressed in hepatocellular carcinoma and that the suppression of TIPRL by small interfering RNA induced continuous activity of JNK (c-Jun N-terminal kinase) and MKK7 (mitogen-activated protein kinase 7) by phosphorylation of MKK7." (PMID 36313570, 2022). "Previously, our team demonstrated that the human TOR signaling regulator protein (hereafter TIPRL) contributes to tumor necrosis factor-related apoptosis-inducing ligand (TRAIL) resistance of hepatocellular carcinomas (HCCs) via the negative regulation of the MKK7/JNK pathway." (PMID 34208132, 2021). "Moreover, previous report demonstrates that TIPRL prevents TRAIL-induced apoptosis through inactivation of MKK7-JNK signaling in hepatocellular carcinoma." (PMID 32719745, 2020). "TIPRL, CD133, and LC3 were shown to be significantly upregulated in hepatocellular carcinomas (HCCs) in comparison to the surrounding normal tissues." (PMID 36212146, 2022). "Here, we demonstrate that TIPRL and LC3 are upregulated and downregulated in hepatocellular carcinomas (HCCs) and intrahepatic cholangiocarcinomas (iCCA), respectively." (PMID 34208132, 2021). "We observed significant upregulations of TIPRL, LC3 and CD133 in hepatocellular carcinomas (HCCs) compared with adjacent normal tissues." (PMID 31727942, 2019). "In this study, we examined the clinical implications of the variables, TIPRL, LC3, CD133, and CD44, all of which have been reported on in terms of their roles in liver cancers and autophagy, including hepatocellular carcinomas (HCCs) and intrahepatic cholangiocarcinomas (iCCA)." (PMID 34208132, 2021). "It is also reported that TIPRL was increased in various carcinomas, including non-small-cell lung carcinoma (NSCLC) and hepatocellular carcinomas (HCC)." (PMID 36212146, 2022). "TIPRL was upregulated in hepatocellular carcinoma (HCC), and it could facilitate TRAIL (a potential anti-cancer agent) resistance of HCC cells." (PMID 33494763, 2021).
lung carcinoma (9 papers, 2019 to 2024). "We believe that our findings can elucidate the regulatory mechanisms underlying the action of TIPRL in lung CSCs, as well as provide potential therapeutic targets for the treatment of lung cancer." (PMID 39076120, 2024). "Former literature testified that TIPRL deficiency promoted the apoptosis of lung cancer H1299 cells disposed by cisplatin, suggesting its important role in lung cancer." (PMID 33494763, 2021). "Here, we investigated the role of TIPRL protein in lung cancer progression and explored the underlying mechanism whereby TIPRL regulates cancer cell survival/progression." (PMID 31862913, 2019). "Therefore, TIPRL knockdown caused lung cancer cells to become more susceptible, promoting cell death by activation of apoptotic signaling." (PMID 31862913, 2019). "TIPRL depletion sensitizes lung CSCs to afatinib‐induced cell death and reduces distal metastasis of lung cancer in vivo." (PMID 39076120, 2024). "TIPRL depletion in CD133+ cells isolated from lung cancer cells also decreased the expression of Bcl2 and HMG20A." (PMID 39076120, 2024). "To demonstrate the clinical significance of TIPRL and CaMKK2 in lung CSCs, we evaluated the expression of two proteins in CSCs freshly isolated from tissues of patients with lung cancer." (PMID 39076120, 2024). "Under physiological conditions, TIPRL depletion decreased the phosphorylation of both CREB sites in several lung cancer cell lines." (PMID 39076120, 2024). "TIPRL also displayed high expression in several lung cancer cell lines, as compared to that in normal epithelial cell lines." (PMID 39076120, 2024). "TIPRL depletion in several lung cancer cell lines also reduced migration and wound‐healing activity versus controls." (PMID 39076120, 2024). "Our results further demonstrated that KCTD21-AS1 regulated TIPRL expression and promoted lung cancer proliferation via ceRNA with miR-519d-5p." (PMID 38383737, 2024). "TIPRL upregulation potentially brings metabolic benefits to lung cancer cells and promotes cancer cells survival." (PMID 38383737, 2024). "EIF2S1 interacts with TOR signaling modulator-like (TIPRL) proteins to induce autophagy and enhance lung cancer malignancy." (PMID 34900672, 2021). "To gain insight into the role of TIPRL in lung cancer progression, we examined the impact of TIPRL knockdown on the proliferation in A549 and H1299 cells through MTT assays." (PMID 31862913, 2019). "Based on our results, we examined the effects of TIPRL knockdown on autophagy levels in order to investigate their relationship in lung cancer." (PMID 31862913, 2019). "First, we examined the levels of TIPRL in clinical lung cancer specimens, and found that tumor tissues had significantly higher levels of TIPRL than normal tissues." (PMID 31862913, 2019). "In this study, we discover a novel molecular process in which TIPRL activates autophagy thereby inhibiting metabolic stress-induced apoptosis in lung cancer cells." (PMID 31862913, 2019). "Overall, the study indicated that TIPRL is a potential regulator of autophagy and an important drug target for lung cancer therapy." (PMID 31862913, 2019). "Overall, our results provide compelling evidence of the importance of TIPRL in regulating stress-induced autophagy and indicate that TIPRL is a potentially effective target for lung cancer therapy." (PMID 31862913, 2019). "Immunohistochemistry (IHC) analysis of 179 paired lung cancer and normal tissues showed that NSCLCs exhibited positive staining for TIPRL." (PMID 31862913, 2019). "Finally, the correlation between TIPRL and CaMKK2 expression was assessed among CSCs isolated from patients with lung cancer and in the data of patients with lung cancer from the TCGA cohort." (PMID 39076120, 2024). "TIPRL is a promising therapeutic target for lung cancer, particularly for CSCs." (PMID 39076120, 2024).
lung carcinoma (continued). "Furthermore, a CRE‐driven reporter assay revealed that the transcriptional activity of CREB decreased after TIPRL depletion in several lung cancer cell lines." (PMID 39076120, 2024). "In addition, KCTD21-AS1 promoted lung cancer proliferation by regulating TIPRL, whereas miR-519d-5p suppressed this proliferation." (PMID 38383737, 2024). "Our findings suggest that the interaction between TIPRL and CaMKK2, which are both highly expressed in lung CSCs and bulk tumor cells, could be related to the poor prognosis of patients with lung cancer." (PMID 39076120, 2024). "Additionally, qRT‐PCR demonstrated increased TIPRL expression in CD133+ CSCs freshly isolated from patients with lung cancer." (PMID 39076120, 2024). "To date, the role of TIPRL in cancer has been documented only in liver and lung cancer." (PMID 32719745, 2020). "In addition, we examined the relationship between TIPRL expression and eIF2α phosphorylation patterns in 41 microarray samples of human lung cancer tissues, using immunohistochemistry." (PMID 31862913, 2019). "Overall, our results strongly indicate that targeting TIPRL could be a potential route for the development of anti-lung cancer therapies." (PMID 31862913, 2019). "Moreover, a substantial G0/G1 cell cycle arrest was observed in TIPRL-knockdown lung cancer cells treated with EBSS." (PMID 31862913, 2019). "Furthermore, we confirmed whether the level of TIPRL expression affects the survival rate of patients with lung cancer, as determined via cohort analysis of The Cancer Genome Atlas (TCGA)." (PMID 39076120, 2024). "Thus, TIPRL and the CaMKK2 signaling axis may be promising targets for overcoming drug resistance and reducing metastasis in lung cancer." (PMID 39076120, 2024). "To determine whether TIPRL involved in stemness and anticancer drug resistance as a target for eliminating lung CSCs, we examined its expression in lung cancer tissues, including lung adenocarcinoma (LUAD), lung squamous cell carcinoma (LUSC), and small cell lung cancer (SCLC)." (PMID 39076120, 2024). "TIPRL depletion significantly reduced the mRNA and protein levels of Bcl2 and HMG20A, among various potential target genes, in several lung cancer cell lines." (PMID 39076120, 2024). "CREB activation upregulates the expression of TIPRL, Bcl2, and HMG20A to maintain the stemness and survival of CSCs, thus promoting tumorigenesis in lung cancer." (PMID 39076120, 2024). "Our results demonstrated that TIPRL was high in NSCLC tissues, which correlated with the poor overall survival of patients with lung cancer." (PMID 38383737, 2024). "In turn, the activated CREB upregulates the expression of TIPRL, Bcl2, and HMG20A to maintain the stemness and survival of CSCs, thus promoting tumorigenesis in lung cancer." (PMID 39076120, 2024). "The positive feedback loop consisting of CREB and TIPRL induces the sustained activation of the CaMKK2‐CaMK4‐CREB axis as a driving force and upregulates the expression of stemness‐ and survival‐related genes, promoting tumorigenesis in patients with lung cancer." (PMID 39076120, 2024). "Interestingly, although TIPRL is reported as a PP2A inhibitory protein and interacts with PP2A, neither eIF2α phosphorylation nor autophagy induction are interrupted in PP2A depleted lung cancer cells." (PMID 31862913, 2019).
liver cancer (5 papers, 2019 to 2024). An epithelial or non-epithelial malignant neoplasm that arises from the liver. "Intriguingly, TIPRL levels were found to be critically associated with liver cancer patients’ survivability, and TIPRL is the key player in liver cancer cell proliferation and viability via stemness and self-renewal induction." (PMID 34208132, 2021). "This study aims to determine prognostic and diagnostic efficacies of TIPRL/LC3/CD133/CD44 for early liver cancer." (PMID 34208132, 2021). "We attempted to analyze diagnostic potentials of TIPRL, LC3, CD133 and the TIPRL/LC3/CD133 levels in liver cancers." (PMID 31727942, 2019). "Together, this suggests the critical diagnostic potential of TIPRL, LC3, CD133 and TIPRL/LC3/CD133 models as biomarkers for early liver cancers." (PMID 31727942, 2019). "Thus, we analyzed early diagnostic potentials of TIPRL, LC3, CD133 and the TIPRL/LC3/CD133 models in grade 1 tissues of liver cancers." (PMID 31727942, 2019). "This evidence suggests that TIPRL promoted liver cancer cell proliferation by inducing cell survival." (PMID 36212146, 2022). "The TIPRL transcription has been found to be the most accurate predictor of survival in patients suffering from liver cancer." (PMID 36212146, 2022). "This indication supports that TIPRL contributed to liver cancer cell proliferation and survival via stemness and self-renewal induction." (PMID 34208132, 2021). "Overall, our data suggests that TIPRL has the most significant effect on liver cancer patients’ survival." (PMID 34208132, 2021). "Here we report the crucial role of TIPRL in liver cancer patients’ survivability and liver cancer cells’ survival." (PMID 34208132, 2021). "TIPRL accelerates liver cancer aggressiveness via the upregulation of the microtubule-associated protein light chain 3 (LC3), an autophagy marker, and CD133 (Prominin-1) expression." (PMID 34208132, 2021). "The TIPRL level has been shown to be the clearest indicator of liver cancer patients’ survivability as a sole covariate." (PMID 34208132, 2021). "In keeping with the significance of TIPRL observed in the public DB, our data showed that TIPRL also had a significant HR on liver cancer patients’ DSS." (PMID 34208132, 2021). "Given the variables’ relationship with the OS of liver cancer patients, we further examined the roles of all five variables, TIPRL, LC3 (ATG7), CD133, CD44, and CD46, in normal liver (Chang), HCC (huh7), and iCCA (SNU1097) cell lines." (PMID 34208132, 2021). "Together, our study provides TIPRL, LC3 and CD133 as biomarkers for early liver cancers through determination of their roles as well as diagnostic efficacies in liver cancers." (PMID 31727942, 2019). "TIPRL downregulation significantly reduces LC3 and CD133 expression, indicating that the TIPRL/LC3/CD133 complex may serve as a valuable biomarker for liver cancer diagnosis." (PMID 38383737, 2024). "TIPRL has a critical role in liver cancer cell survival via stemness and self-renewal induction." (PMID 34208132, 2021). "Additionally, in sorafenib-treated liver cancer patients, TIPRL, LC3, and CD133, showed a substantial HR and 95% CI, except for CD44." (PMID 34208132, 2021). "This study assessed the human TOR signaling regulator (TIPRL)/microtubule-associated light chain 3 (LC3)/prominin-1 (CD133)/cluster of differentiation 44 (CD44) as potential diagnostic and prognostic biomarkers for early liver cancer." (PMID 34208132, 2021). "Furthermore, our study provides evidence for the significant prognostic and diagnostic efficiencies of TIPRL/LC3/CD133/CD44, either individually or in conjunction, to detect early liver cancer." (PMID 34208132, 2021). "Recently, we reported the involvement of TIPRL/LC3/CD133 in liver cancer aggressiveness." (PMID 34208132, 2021).